AFP (alpha fetoprotein)
Diseases named in the same sentence as AFP in open-access papers (continued):
Sharing a sentence is not in itself a finding about the gene and the disease.
Hypercholesterolemia (8 papers, 2013 to 2024). An increased concentration of cholesterol in the blood. "Paraneoplastic hypercholesterolemia was similarly strongly associated with increased AFP level but only weakly associated with advanced TNM stage." (PMID 24396608, 2013). "Moreover, a correlation was noted between hypercholesterolemia and the AFP value, notably strongly associated with a tumor size exceeding 5 cm, indicating that hypercholesterolemia is more closely associated with tumor size." (PMID 38674198, 2024). "While paraneoplastic hypercholesterolemia in our patients was strongly associated with elevated AFP levels (P < 0.001), its association with TNM stage and its effect on survival were only just within statistical significance (P = 0.049 and P = 0.047, resp., for TNM stage and survival)." (PMID 24396608, 2013). "Initial clinical findings revealed elevated liver enzymes, a mildly enlarged hyperechoic liver, hypercholesterolemia, and borderline alpha-fetoprotein values." (PMID 38929922, 2024). "Laboratory results showed elevated AFP 23.1 ng/mL (normal range < 15 ng/mL) and normal albumin of 4.61 g/dL (normal range: 3.5–5.5 g/dL), without hypercholesterolemia." (PMID 35203940, 2022).
Hypoglycemia (8 papers, 2014 to 2024). A decreased concentration of glucose in the blood. "Reduced expression of key gluconeogenic genes including Pck1, G6Pc, and Pfkfb3 in L-GRKO mice is linked to fasting hypoglycemia, and around half of newborn albumin-alpha-fetoprotein-driven L-GRKO mice die within 48 h after birth, possibly due to hypoglycemia." (PMID 33133019, 2020). "Reported clinical manifestations included cholestasis (13/13, 100%), elevated AFP (11/11, 100%), coagulopathy (11/11, 100%), hypoglycemia (9/13, 69%), failure to thrive (8/13, 62%), splenomegaly (7/13, 54%), hyperammonemia (7/13, 54%), and hepatomegaly (6/13, 46%)." (PMID 38641832, 2024). "In addition, elevated alpha‐fetoprotein (83.33%, 20/24), hypoglycemia (45.83%, 11/24), cholestasis (20.83%, 5/24), jaundice (75%, 18/24), coagulopathy (75%, 18/24), vomiting (66.67%, 16/24), and poor feeding (70.83%, 17/24) were also presented in patients." (PMID 33205917, 2020). "Patients present severe hypoglycemia with lactic acidosis, elevated ALT and AST levels, elevated GGT, and high alpha-fetoprotein (AFP)." (PMID 39336844, 2024). "Laboratory findings revealed hypoglycaemia, and patients with liver impairment had raised plasma levels of bilirubin, transaminases, GGT, ferritin, alpha fetoprotein and coagulopathy." (PMID 23714749, 2014).
multiple myeloma (8 papers, 2015 to 2025). "Mice were immunized with a fucosylated AFP peptide, and harvested spleen cells were fused with P3U1 mouse myeloma cells." (PMID 31451706, 2019). "The blood test results showed negative tumor markers (alpha-fetoprotein [AFP], carcinoembryonic antigen [CEA], carbohydrate antigen 19-9 [CA19-9], soluble interleukin-2 receptor [sIL-2R]), nor markers associated with multiple myeloma (immunoglobulin [Ig] G, A, M, urinary Bence-Jones protein)." (PMID 40519416, 2025).
non-seminomatous germ cell tumors (8 papers, 2000 to 2026). "We present a case of a 36-year-old male found to have a nonseminomatous germ cell tumor (NSGCT) with alpha-fetoprotein levels (AFP) of 737.9 ng/mL and beta-human chorionic gonadotropin (β-HCG) of 692 IU/mL." (PMID 39677122, 2024). "In non-seminomatous germ cell tumors (NSGCT), elevated concentrations of β-hCG, AFP, and LDH are observed in 53%, 60%, and 39% of cases, respectively." (PMID 38396829, 2024). "Pure seminoma may be associated with a rise in blood levels of human chorionic gonadotrophin (HCG), which may also be raised in non-seminomatous germ cell tumors (NSGCTs); however, raised alphafetoprotein (AFP) would suggest a non-seminomatous origin and pathology should be reviewed carefully." (PMID 20535292, 2010).
spina bifida (8 papers, 2008 to 2025). A congenital neural tube defect in which vertebrae are not fully formed. "The mean for spina bifida at each week of gestation can be derived by regression of the observed gestation-specific MoM from the UK Collaborative AFP Study, increased to allow for the reduced BPD—This also affects closed spina bifida." (PMID 26237388, 2014). "Since that period there have been three developments leading to improved performance of AFP screening for spina bifida." (PMID 26237388, 2014). "A normal alpha fetoprotein test (AFP) result had been obtained by her obstetrician, suggesting a closed form of spina bifida." (PMID 38352135, 2024).
type 2 diabetes mellitus (8 papers, 2021 to 2024). A type of diabetes mellitus that is characterized by insulin resistance or desensitization and increased blood glucose levels. "Among age, sex, AFP, albumin, CP score, receipt of surveillance, platelets, total bilirubin, type 2 diabetes, and initial tumor size, we found that higher AFP (P = 0.048), lower albumin at presentation (P = 0.028), and lower initial tumor size (P = 0.025) were associated with higher TGR." (PMID 34966854, 2021).
coagulopathy (7 papers, 2014 to 2025). "What was universally noted in all treated patients is the rapid decline in alpha fetoprotein and normalization of coagulopathy." (PMID 35536841, 2022). "Furthermore, hyperlactatemia and hyperammonemia were detected with extremely elevated alpha-fetoprotein, decreased vitamin D, laboratory signs of coagulopathy, and increased ALP levels." (PMID 41362306, 2025). "Coagulopathy is very common and alpha-fetoprotein is uniformly elevated." (PMID 35536841, 2022).
embryonal tumors (7 papers, 2017 to 2025). "Screening for embryonal tumors through alpha-fetoprotein (AFP) markers and abdominal ultrasounds was started." (PMID 38919860, 2024). "Upregulation of AFP is commonly observed in hepatocyte regeneration, hepatocarcinogenesis, and embryonic cancers, which suggests it can function as a biomarker for diagnosing HCC." (PMID 36769597, 2023).
hemangioma (7 papers, 2015 to 2025). A benign vascular lesion characterized by the formation of capillary-sized or cavernous vascular channels. "The immunoreactivity of the hemangioma cells for AFP in this case suggested the AFP-producing nature of the umbilical cord hemangioma." (PMID 26337640, 2015). "The present case is one of the largest umbilical cord hemangiomas reported in the literature, and the first hemangioma case with MS-hCG elevation, extramedullary hematopoiesis, and positive AFP staining in the cord hemangioma." (PMID 26337640, 2015). "Similarly, among the control group of patients with hemangioma, 73 patients were tested more than twice for AFP." (PMID 35862314, 2022). "However, hepatic hemangiomas are well-known benign lesions that do not cause AFP elevation, and CT was commonly performed for the evaluation of hemangiomas." (PMID 35862314, 2022). "The longitudinal follow-up AFP in patients with hemangioma was not significantly changed over time (p = 0.148)." (PMID 35862314, 2022). "However, HAS and HEHE did not significantly differ from benign hemangiomas in terms of age of onset, sex, lesion size, lesion number, PLT, coagulation function, AFP, or CEA." (PMID 32600273, 2020).
Hyperbilirubinemia (7 papers, 2016 to 2024). An increased amount of bilirubin in the blood. "As expected, high AFP levels (>200 ng/mL) heralded a poor OS, thus confirming that AFP-secreting HCCs have a more aggressive development, showing more frequently multifocality, portal vein invasion and hyperbilirubinemia." (PMID 34072309, 2021). "If the MoM values were compared with each other, the ratios of AFP/E3 and hCG/E3 were the most helpful to predict the neonatal hyperbilirubinemia (Table-IV)." (PMID 29067077, 2017). "Because we thought that the neonatal hyperbilirubinemia which is an abnormality of the liver function could be understood with the level of serum E3, AFP, hCG and the ratio of these hormones during second trimester." (PMID 29067077, 2017). "The ratios of AFP/E3 and hCG/E3 were the most helpful to predict the neonatal hyperbilirubinemia." (PMID 29067077, 2017).
Immunodeficiency (7 papers, 2014 to 2025). Failure of the immune system to protect the body adequately from infection, due to the absence or insufficiency of some component process or substance. "Collectively, the immunodeficiency manifestations—decreased IgA, reduced B lymphocytes, a slight increase in IgM, and significantly elevated AFP levels—support the diagnosis of A-T caused by novel frameshift mutations of the ATM gene in this Chinese family." (PMID 39678378, 2024). "A typical laboratory profile in A-T includes decreased IgA and IgG levels, as well as elevated AFP, which reflect a combination of immunodeficiency and impaired DNA repair mechanisms." (PMID 41451872, 2025). "Immunological studies confirmed a marked immunodeficiency in all patients, evidenced by decreased IgA and IgG levels and elevated alpha-fetoprotein." (PMID 41451872, 2025). "Both siblings presented with immunodeficiency, characterized by low immunoglobulin A (IgA) levels, slightly elevated IgM levels, and elevated alpha-fetoprotein (AFP)." (PMID 39678378, 2024). "Patients with A-T can also have impaired cellular and humoral immunity (IgA, IgE, or IgG2 immunodeficiency) and elevated serum alpha-fetoprotein (AFP), which can be useful for the diagnosis." (PMID 25374730, 2014).
lung adenocarcinoma (7 papers, 2011 to 2026). A carcinoma that arises from the lung and is characterized by the presence of malignant glandular epithelial cells. "This study presents a retrospective analysis of clinical features associated with STAS in stage I lung adenocarcinoma, utilizing seven risk factors (CEA, vascular convergence, proGRP, age, AFP, smoking history, and CTR) to develop predictive models." (PMID 41234731, 2025). "After analyzing clinical data from 1153 patients with lung adenocarcinoma, we found that the concentrations of AFP, CEA, CYFRA 21-1, CA-125, CA-153, and TPSA were significantly elevated in patients with OM." (PMID 32685054, 2020). "Immnohistochemical staining for AFP revealed positive staining of a number of tumor cells for AFP, leading to the diagnosis of AFP-producing lung adenocarcinoma." (PMID 21554678, 2011). "Further accumulation of cases and analysis of data on the malignancy grade and long-term prognosis of AFP-producing lung adenocarcinoma would be desirable." (PMID 21554678, 2011). "The tumor was thus diagnosed as an AFP-producing lung adenocarcinoma." (PMID 21554678, 2011). "Therefore, combination therapy involving an AFP-targeted drug and an immune checkpoint inhibitor may be a viable treatment strategy for AFP-positive fetal lung adenocarcinoma." (PMID 41717591, 2026). "In this study, the first part would detail the correlations between serum CEA, serum AFP, serum CA125, serum CA15‐3, serum CA19‐9 and tumor size, TNM stage of lung adenocarcinoma." (PMID 31881123, 2020). "Serum AFP was not correlated with tumor size, T stage, N stage, and M stage of lung adenocarcinoma." (PMID 31881123, 2020).
rhabdoid tumor (7 papers, 2022 to 2025). An aggressive malignant embryonal neoplasm usually occurring during childhood. "After AFP correlation, radiologists identified 3/6 rhabdoid tumors accurately, with a sensitivity of 50% [95% CI, 11.8–88.9%]." (PMID 38831055, 2024). "Three cases with predominant cystic/necrotic components and metastases were accurately diagnosed as rhabdoid tumors after AFP levels, while the remaining three remained indeterminate." (PMID 38831055, 2024). "Patients with HB with SCU component or low AFP should be assessed for SMARCB1 mutations and, if confirmed, treated as rhabdoid tumors." (PMID 36672416, 2023). "Patients with AFP less than 100 ng/mL did not have a poor prognosis following the exclusion of tumors reclassified as rhabdoid tumors and those with erroneously low AFP levels due to the “hook” effect." (PMID 36672416, 2023). "Molecular characterization of SCU HBs revealed that a proportion of HBs with SCU histology are actually primary rhabdoid tumors with characteristic loss-of-function variants or deletions of the SMARCB1 gene, loss of INI1, low AFP levels, and poor outcomes." (PMID 36672416, 2023). "Fourteen patients [including 1 patient with a tumor re-classified as nested epithelial stromal tumor (NEST) upon consensus review] had an AFP less than 100 ng/mL; eight additional patients with AFP less than 100 ng/mL had rhabdoid tumors." (PMID 36672416, 2023). "In the CHIC database, eleven patients with either low AFP or SCU histology were re-classified as rhabdoid tumors." (PMID 36672416, 2023). "With other differential diagnoses of a mesenchymal hamartoma and a rhabdoid tumor also present in the under 2-year population, we evaluated whether the lesions that are confidently diagnosed on imaging with AFP correlation could avoid a biopsy." (PMID 38831055, 2024). "It is important to exclude rhabdoid tumors in patients diagnosed with HB with AFP less than 100 ng/mL (or normal for gestational age) and in patients with tumors histologically diagnosed as HB with SCU component, since the treatment for these patients should be very different." (PMID 36672416, 2023). "It should be kept in mind that patients with very low AFP levels (<100 ng/mL) may have small cell undifferentiated type or rhabdoid tumors." (PMID 36262102, 2022). "Upon retrospective review, they were re-classified as rhabdoid tumors (n = 11), HB with SCU component (n = 41), and HB with low AFP (n = 14)." (PMID 36672416, 2023). "Ongoing and future large, controlled studies including central consensus review, AFP at diagnosis for every patient, and INI1 immunohistochemistry or SMARCB1 genetic testing for suspected rhabdoid tumor cases would be required to confirm these findings." (PMID 36672416, 2023). "Overall survival was 0% for patients with rhabdoid tumors, 76% for patients with HB with SCU component, and 64% for patients with HB with AFP less than 100 ng/mL." (PMID 36672416, 2023). "MUC16, OPN, AFP, and MSLN gene expression were highly expressed in all malignant rhabdoid tumor cell lines (CHLA-02, CHLA-05, and G401)." (PMID 35954348, 2022). "AFP at diagnosis was not reported in 38 of the 66 patients analyzed (AFP level was reported in nine patients with rhabdoid tumors, five patients with HB with SCU component, and 14 patients with low AFP)." (PMID 36672416, 2023). "The AFP at diagnosis was less than 100 ng/mL for all but one patient for which AFP was minimally elevated for age (AFP was not reported in two patients with rhabdoid tumor)." (PMID 36672416, 2023). "Neither the presence of SCU component nor AFP less than 100 ng/mL confer poor prognosis in patients with HB, once rhabdoid tumors are ruled out by immunohistochemical or molecular testing." (PMID 36672416, 2023). "Fourteen patients had AFP levels less than 100 ng/mL at diagnosis and were not identified as rhabdoid tumors nor HB with SCU component." (PMID 36672416, 2023).
rhabdoid tumor (continued). "After excluding rhabdoid tumor cases from the analyzed group, it was found that the presence of the small cell undifferentiated subtype or low AFP levels no longer had poor prognostic significance." (PMID 37686577, 2023). "AFP, MSLN, MUC16, OPN, and MT1-MMP/MMP14 may serve as biomarkers for human malignant rhabdoid tumor detection and therapeutic targets." (PMID 35954348, 2022). "AFP gene and protein expression may serve as a valuable biomarker for malignant rhabdoid tumors due to its much higher expression levels compared to nonmalignant cells." (PMID 35954348, 2022).
trisomy 18 (7 papers, 2010 to 2023). Trisomy 18 is a chromosomal abnormality associated with the presence of an extra chromosome 18 and characterized by growth delay, dolichocephaly, a characteristic facies, limb anomalies and visceral malformations. "The AUCs for AFP-L2 in the screening of trisomy 21, 18 fetuses were higher than those for AFP in trisomy 21, and lower than those for trisomy 18 (0.785 and 0.758 vs, 0.613; 0.775 and 0.754 vs, 0.869, respectively)." (PMID 35948592, 2022). "The fetus was identified as screen-positive for Edward's syndrome (trisomy 18), with low uE3, normal AFP and hCG levels." (PMID 21031058, 2010).
adenoma (6 papers, 2012 to 2025). A neoplasm arising from the epithelium. "When the AFP check value was 12.3 (ng/mL) and the colonoscopy polyp = 3 (an adenoma is identified using colonoscopy), the decision tree identified eight people, which reflected the confidence of the rule." (PMID 32455870, 2020). "The liver transplant is considered to be the ultima ratio in case of solid, very large, unresectable, symptomatic adenomas, in distinct adenomatosis of the liver with AFP increase or in case of multiple, progressive growing recurrence adenomas." (PMID 22927707, 2012). "In order to detect malignant transformation of adenomas in patients after resection, a strict followup is needed, containing annual imaging and regular AFP determination." (PMID 22927707, 2012). "The majority (>83 ± 5%) of tumors from WT mice expressed AFP and YAP, indicating that alcohol-induced injury facilitates the development of HCC vs. adenomas." (PMID 40529212, 2025). "Among these samples, the levels of three circulating tumor markers, CEA, AFP, and CA19-9, were also measured for 106 CRC, 28 advanced adenoma, and 20 small polyp patients and all control subjects." (PMID 33977101, 2021).
alcoholic cirrhosis (6 papers, 2015 to 2024). "The risk of HCC can be stratified by using a combination of readily available clinical parameters (age, AFP level, and albumin level) in patients with alcoholic cirrhosis." (PMID 35110551, 2022). "In conclusion, the risk of HCC can be stratified by using a combination of readily available clinical parameters (age, AFP level, and albumin level) in patients with alcoholic cirrhosis." (PMID 35110551, 2022). "For instance, increased serum AFP may be detected in patients with drug abuse, alcoholic cirrhosis and other states of chronic liver damage." (PMID 29390333, 2017). "Recently, osteopontin (OPN) has attracted attention as a promising biomarker, with some potential advantages compared to alpha-fetoprotein (AFP), but its role in the context of alcoholic cirrhosis has never been assessed." (PMID 26122937, 2015).
Anxiety (6 papers, 2008 to 2025). Intense feelings of nervousness, tension, or panic often arise in response to interpersonal stresses. "Furthermore, we identified an association between serum AFP levels and the presence of symptoms of anxiety and depression." (PMID 39741695, 2024). "In multivariate analysis, serum AFP level (β ± SE = 0.34 ± 0.15, p = 0.03), as well as being unable to work or being disabled (β ± SE = 3.63 ± 1.81, p = 0.04), were the two variables independently positively associated with a high anxiety and depression score." (PMID 39741695, 2024). "Using HADS, 52% of the patients had anxiety/depression that was correlated with alpha-fetoprotein level (p = 0.03)." (PMID 39741695, 2024). "To note, serum AFP level was significantly associated with a higher rate of depression (β ± SE = 0.22 ± 0.08, p = 0.006) but not of anxiety (β ± SE = 0.12 ± 0.09, p = 0.19) defined by the HADS scale." (PMID 39741695, 2024). "Second, further examination including AFP and ultrasound may result in psychological burden, blooding, and anxiety." (PMID 35047391, 2021).